LINC00309 (long independently transcribed non-coding RNA 309)
Synonyms: NCRNA00309
Gene: Long non-coding RNA gene on chromosome 2 (64,185,078 to 64,205,485, reverse strand). Ensembl gene ENSG00000230923.
Diseases named in the same sentence as LINC00309 in open-access papers:
LINC00309 is named in the same sentence as 2 diseases in open-access papers, as found by Europe PMC text mining. Sharing a sentence is not in itself a finding about the gene and the disease. The quoted sentences say what the papers report.
breast carcinoma (1 paper, 2019). "In breast cancer, Linc00309 is significantly associated with poor prognosis and may represent a new marker of prognosis." (PMID 31406486, 2019). "Kaplan–Meier and Cox risk proportion model were applied to disclose the function of LINC00309 for breast cancer prognosis." (PMID 31406486, 2019). "This suggested that LINC00309 could be a new marker of prognosis in breast cancer." (PMID 31406486, 2019).
LINC00309 also shares sentences with these, for which no sentence is quoted: tumor (1 paper).